EIF4A1 (eukaryotic translation initiation factor 4A1)
Description:
ATP-dependent RNA helicase which is a subunit of the eIF4F complex involved in cap recognition and is required for mRNA binding to ribosome. In the current model of translation initiation, eIF4A unwinds RNA secondary structures in the 5'-UTR of mRNAs which is necessary to allow efficient binding of the small ribosomal subunit, and subsequent scanning for the initiator codon. As a result, promotes cell proliferation and growth.
Synonyms: eIF-4A-I; eIF4A-I; DDX2A; EIF4A; EIF-4A
Tractability: Small molecule: a structure with a bound ligand is known; a high-quality ligand is known; it has a binding pocket of medium quality; it belongs to a druggable protein family. Antibody: UniProt places it where antibodies can reach, with high confidence; its Gene Ontology location is reachable by antibodies, with high confidence. PROTAC: UniProt records ubiquitination sites on it; ubiquitination databases record sites on it; its protein half-life has been measured; a small molecule that binds it is known.
Target class: Enzyme; Hydrolase
Chemical probes: SILVESTROL
Gene: Protein-coding gene on chromosome 17 (7,572,760 to 7,579,006, forward strand). Ensembl gene ENSG00000161960.
Subcellular location: Cytoplasm, perinuclear region; Cell membrane; Cytoplasm, Stress granule
Subcellular location (Human Protein Atlas): Cytosol
Pathways (Reactome):
Metabolism of proteins: Activation of the mRNA upon binding of the cap-binding complex and eIFs, and subsequent binding to 43S; GTP hydrolysis and joining of the 60S ribosomal subunit; L13a-mediated translational silencing of Ceruloplasmin expression; Ribosomal scanning and start codon recognition; Translation initiation complex formation
Developmental Biology: M-decay: degradation of maternal mRNAs by maternally stored factors; Z-decay: degradation of maternal mRNAs by zygotically expressed factors
Disease: Dengue Virus Genome Translation and Replication
Immune System: ISG15 antiviral mechanism
Metabolism of RNA: Deadenylation of mRNA
Gene Ontology:
Molecular function: double-stranded RNA binding; protein binding; RNA binding; translation initiation factor activity; helicase activity; mRNA binding; RNA cap binding; translation factor activity, RNA binding; ATP binding; ATP hydrolysis activity; nucleic acid binding; RNA helicase activity
Biological process: cytoplasmic translational initiation; positive regulation of transcription by RNA polymerase II; translational initiation
Cellular component: cytoplasm; extracellular exosome; membrane; nuclear stress granule; nucleus; perinuclear region of cytoplasm; plasma membrane; cytosol; eukaryotic translation initiation factor 4F complex; cytoplasmic stress granule
Genetic constraint (gnomAD): Loss-of-function variants: 11 observed, 54.01 expected, observed/expected ratio (o/e) 0.2, 90% interval 0.13 to 0.34. The synonymous counts are far from expectation, so gnomAD's model fits this gene poorly and the ratio says little. Missense variants: 213 observed, 547.16 expected, observed/expected ratio (o/e) 0.39, 90% interval 0.35 to 0.44. Synonymous variants: 237 observed, 191.52 expected, observed/expected ratio (o/e) 1.24, 90% interval 1.11 to 1.38.
Homologues: Orthologues: dog EIF4A1 (100% identical), mouse Eif4a1 (100% identical), rat Eif4a1 (99% identical), guinea pig EIF4A1 (98% identical), pig EIF4A1 (98% identical), tropical clawed frog eif4a1 (94% identical), Drosophila melanogaster eIF4A (72% identical), Caenorhabditis elegans inf-1 (69% identical). Paralogues in human: EIF4A2 (90% identical), EIF4A3 (67% identical), DDX19B (38% identical), DDX19A (38% identical), DDX25 (37% identical), DDX39A (35% identical), DDX39B (35% identical), DDX3X (35% identical), DDX6 (35% identical), DDX3Y (34% identical), DDX17 (33% identical), DDX43 (33% identical), and 26 more.
Diseases named in the same sentence as EIF4A1 in open-access papers:
EIF4A1 is named in the same sentence as 65 diseases in open-access papers, as found by Europe PMC text mining. Sharing a sentence is not in itself a finding about the gene and the disease. The quoted sentences say what the papers report.
gastric cancer (16 papers, 2018 to 2025). A primary or metastatic malignant neoplasm involving the stomach. "CircDLST/miR-489-3p/EIF4A1 regulated the proliferation and apoptosis of gastric cancer cells, affecting the anti-gastric cancer effect of Astragaloside IV." (PMID 39314750, 2024). "Similar to the role of miR-133a, miR-1284 can directly inhibit the expression of EMT related genes c-Myc and MMP12 by inhibiting eIF4A1 in gastric cancer." (PMID 38028556, 2023). "Several studies have reported the tumor−promoting effect of EIF4A1 in gastric cancer and breast cancer by promoting oncogene translation." (PMID 35592316, 2022). "Circ-BPTF promotes bladder cancer progression and recurrence through miR-21-5p/RAB27A axis, while Circ_0008035 promotes gastric cancer cell proliferation and inhibits apoptosis through miR-599/EIF4A1 axis." (PMID 35444695, 2022). "Another study showed that EIF4A1 contributes to gastric cancer progression by binding miR-1284 with high specificity." (PMID 33461173, 2021). "ASIV has also been shown to inhibit the progression of gastric cancer (GC) by targeting circDLST, which modulates the miR-489-3p/EIF4A1 signaling pathway." (PMID 40362487, 2025). "As an important component of eIF4F, eIF4A1 plays a vital role in malignant transformation and progression, and recent evidence has shown that eIF4A1 is dysregulated in gastric cancer (GC), colorectal cancer, cervical cancer, hepatocellular carcinoma, ovarian cancer, and other cancers." (PMID 34869305, 2021). "Accordingly, a negative prognostic role of eIF4A1 has been previously detected in other tumor types, such as lung adenocarcinoma, clear cell renal carcinoma, and gastric cancer, among many others." (PMID 36768380, 2023). "EIF4A1, a eukaryotic translation initiation factor, plays vital roles in protein translation initiation, participates in epithelial-to-mesenchymal transition (EMT) and is related to a poor prognosis in patients with gastric cancer." (PMID 33461173, 2021). "In addition, ectopic expression of miR-126, miR-647 and miR-1284, which are evidently downregulated in drug-resistant SGC7901/VCR gastric cancer cells, could sensitize gastric cancer cells to VCR by inhibiting expression of EZH2, ANK2 and EIF4A1, respectively." (PMID 32192494, 2020). "The expression of miR-1284 was reduced in gastric cancer (GC) tissue specimens with metastasis and vincristine-resistant (VCR) GC SGC7901 cells, and overexpression of miR-1284 reversed the chemoresistance of SGC7901/VCR cells by targeting EIF4A1." (PMID 29899164, 2018).
breast carcinoma (11 papers, 2015 to 2024). "We then sought causative relationships among mediators of eIF4A1 helicase function, cell growth and the cell cycle by screening a panel of breast cancer cell lines." (PMID 25611378, 2015). "Increasing evidence has highlighted the oncogenic role of EIF4A1 in various cancers, including prostate, pancreatic, and breast cancer." (PMID 37654606, 2023). "For instance, inhibition of EIF4A1 enhanced cell apoptosis and reduced tumor growth in breast cancer and prostate cancer." (PMID 35435117, 2022). "EIF4A1 played a key role in different cancers, such as lymphoma, breast cancer, and prostate cancer." (PMID 35435117, 2022). "Alterations in EIF4A1 activity-modulating proteins expression have been observed in the tumourigenesis of melanoma, breast cancer, and pancreatic cancer." (PMID 32671073, 2020). "We went on to show that eIF4A1 activity is limiting for cell growth and cycling in cultured breast cancer cells." (PMID 25611378, 2015). "Upon interrogating zotatifin target abundance in different breast cancer subtypes, we found that the protein level of EIF4A1 is higher in TNBC as compared with non-TNBC." (PMID 37874652, 2023).
hepatocellular carcinoma (7 papers, 2009 to 2023). A malignant tumor that arises from hepatocytes. "Expression of Eif4a1 is associated with increased metastasis in certain cancers, can stimulate cell growth in hepatoma cells and is enriched in populations of human ES cells." (PMID 19134196, 2009). "EIF4A1 is overexpressed in hepatocellular carcinoma and is an early marker of distant metastases of non-small cell lung cancer." (PMID 22415234, 2012).
melanoma (7 papers, 2002 to 2024). A malignant, usually aggressive tumor composed of atypical, neoplastic melanocytes. "Another independent confirmation of eIF4F-dependent regulation of DUSP6 levels in melanoma cells was provided by transient transfection of siRNAs specific for the eIF4A1, eIF4G1, and eIF4E transcripts." (PMID 39436655, 2024). "The tetracycline-inducible expression system was established in melanoma cells, and three fragments of the 5′-, central-, and 3′-portion of the eIF-4A1 cDNA were subcloned in antisense and in sense orientation after a tetracycline inducible promoter." (PMID 12085193, 2002). "Only limited data were available about the expression of translation factors in melanoma as well as about the role of eIF-4A1 in tumorigenesis." (PMID 12085193, 2002). "The data presented here demonstrate that human melanoma cells can be targeted by antisense constructs, even when the targeted mRNA is strongly expressed as in the case of eIF-4A1." (PMID 12085193, 2002). "In human melanoma cells, we have previously reported consistent overexpression of translation initiation factor eIF-4A1." (PMID 12085193, 2002). "In agreement, we found significant antiproliferative effects after induction of antisense RNA against eIF-4A1, strongly suggesting that in human melanoma cells, eIF-4A plays at least an auxiliary role in regulation of cellular proliferation." (PMID 12085193, 2002). "Similarly, the silencing of eIF4A1 in WM858 cells significantly decreases melanoma proliferation and invasion." (PMID 34869305, 2021). "Other studies in melanoma, B-cell malignancies, hypopharynx cancer, pancreatic cancer, and endometrioid endometrial cancer have indicated tumor promoter roles for the eIF4A1 protein." (PMID 34869305, 2021). "Our data suggest that a concerted action of several translation factors, including eIF-4A1, may be decisive for the translational contribution to melanoma development." (PMID 12085193, 2002). "In the present paper, we addressed the question whether we can confer inhibitory effects on melanoma cells by obstructing eIF-4A1 gene expression using transient and stable transfection of antisense constructs against eIF-4A1." (PMID 12085193, 2002). "In the present study, we investigated whether eIF-4A1 can be targeted in cultured melanoma cells by overexpression of antisense RNA using antisense plasmid constructs." (PMID 12085193, 2002). "Translation initiation factor eIF-4A1 contributes to the control of melanoma cell proliferation and may be taken into consideration when scheduling new therapeutic approaches targeting the translational control." (PMID 12085193, 2002). "In a previous study, we reported consistent upregulation of eIF-4A1 mRNA in melanoma cell lines, as compared to normal human melanocytes, which led us suggest that eIF-4A1 may be related to melanoma cell transformation." (PMID 12085193, 2002). "The only limited antiproliferative effect which was obtained in all transfection experiments (up to 10% reduction) has to be seen in relation to the relatively high expression of eIF-4A1 mRNA in melanoma cells, comparable to the expression of major proteins as glycolytic enzymes and β-tubulin." (PMID 12085193, 2002). "The analysis revealed that the genetic disruption of the EIF4A1, EIF4E, and EIF4G1 genes encoding the eIF4A, eIF4E, and eIF4G subunits decreased fitness of most melanoma cell lines, arguing against the use of knock-out cell lines to study the impact of eIF4F inhibition in melanoma." (PMID 39436655, 2024). "Silvestrol targets at EIF4A1 and EIF4A2, silvestrol also have the potential to act as cancer immunotherapies in melanoma." (PMID 31088567, 2019). "This assumption is further promoted by the finding that only eIF-4A1 but none of the other group 4 translation factors (eIF-4E, eIF-4B, eIF-4G, eIF-4A2) was significantly upregulated in melanoma cells as compared to normal melanocytes." (PMID 12085193, 2002).
melanoma (continued). "Due to the rather limited growth effect obtained after stable transfection, antisense gene therapies exclusively against eIF-4A1 would be not sufficient in melanoma, however, they may be contributory and helpful in combination with other gene targets." (PMID 12085193, 2002).
pancreatic cancer (7 papers, 2019 to 2023). "EIF4A1 is implicated in epithelial-mesenchymal transition as well as metastasis of gastric and pancreatic cancers." (PMID 36185235, 2022). "eIF4A1 and c-myc promoted epithelial mesenchymal transformation and metastatic ability of pancreatic cancer cells, while eIF4A1 alone upregulation reduced the inhibitory effect of c-myc downregulation on epithelial mesenchymal transformation and metastasis." (PMID 38028556, 2023). "Western blot analysis showed that eIF4A1 was notably more highly expressed in the aggressive pancreatic cancer cell line AsPC-1 and relatively less expressed in the indolent Capan-2 cell line and normal HPDE cells." (PMID 34906136, 2021). "Loss of eIF4A1 and c-MYC decreased the EMT and metastasis capabilities of pancreatic cancer cells, whereas upregulation of eIF4A1 attenuated the inhibition of EMT and metastasis induced by c-MYC downregulation." (PMID 34906136, 2021). "Before exploring the role of eIF4A1 and c-MYC in the regulatory effect in pancreatic cells, we analyzed eIF4A1 expression in the pancreatic cancer cell lines Panc-1, Capan-2, AsPC-1, and MiaPaca-2, and in the normal pancreatic ductal epithelial cell line HPDE." (PMID 34906136, 2021). "We ranked the differential expression of all eIFs and the results showed that the expression level of eIF4A1 in pancreatic tumor tissues was significantly higher than that in normal tissues." (PMID 34906136, 2021). "Mechanistically, PHGDH interacted with the translation initiation factors eIF4A1 and eIF4E and facilitated the assembly of the translation initiation complex eIF4F to promote the development of pancreatic cancer." (PMID 30744688, 2019). "The eIF4A1 inhibitor Rocaglamide (RocA) and the c-Myc inhibitor Mycro3, alone or in combination, significantly reduced the expression levels of markers of epithelial mesenchymal transition in pancreatic cancer cells." (PMID 38028556, 2023). "Treatment with the eIF4A1 inhibitor rocaglamide (RocA) or the c-MYC inhibitor Mycro3 either alone or in combination significantly decreased the expression level of EMT markers in pancreatic cancer cells in vitro." (PMID 34906136, 2021). "To elucidate the mechanism by which eIF4A1 regulates the biological behavior of tumor cells, we searched the GEO database for all ribosome profiling data that included pancreatic cancer cells, and ultimately, dataset GSE120159 was selected for further analysis." (PMID 34906136, 2021). "Inhibiting PHGDH expression and disrupting the interactions between PHGDH and eIF4A1/eIF4E provide new prospects for anti-tumor therapeutics designs, which are meaningful for improving the pancreatic cancer treatment effect and prolonging the overall survival of clinical patients." (PMID 30744688, 2019). "Besides catalyzing serine synthesis, PHGDH promotes pancreatic cancer development through enhancing the translation initiations by interacting with eIF4A1 and eIF4E." (PMID 30744688, 2019). "In pancreatic cancer, PHGDH enhances mRNA translation by interacting with eIF4A1 and eIF4E, thereby promoting cancer development." (PMID 36578934, 2022). "Overexpression of eIF4A1 downregulated E-cadherin expression through the c-MYC/miR-9 axis, which promoted EMT and metastasis of pancreatic cancer cells." (PMID 34906136, 2021). "In this study, we found that eIF4A1 overexpression rescued the diminished EMT and metastasis capabilities of c-MYC knockdown pancreatic cancer cells in vitro and in vivo." (PMID 34906136, 2021). "Collectively, we demonstrated that eIF4A1 overexpression downregulated E-cadherin expression through the c-MYC/miR-9 axis, which promoted EMT and the metastasis of pancreatic cancer cells in vitro and in vivo." (PMID 34906136, 2021). "Expression regulation and pharmacological inhibition of eIF4A1 and c-MYC were performed to determine their role in migration, invasion, and metastasis in pancreatic cancer cells in vitro and in vivo." (PMID 34906136, 2021).
colorectal cancer (6 papers, 2019 to 2023). A primary or metastatic malignant neoplasm that affects the colon or rectum. "Circ-0008035 sponge miR-599 to improve the expression of EIF4A1 advanced the progression of colorectal cancer." (PMID 35170374, 2022). "Considering the results related to EIF2S3 and EIF4A1 mRNA changes in the patients with colorectal cancer, the increase in mRNA levels in peripheral blood samples is remarkable." (PMID 33237662, 2021). "Further study is therefore required to understand EIF4A1 mRNA changes in peripheral blood samples of colorectal cancer patients." (PMID 33237662, 2021). "According to the results presented in this study, the increase in EIF4A1 mRNA level in peripheral blood samples stands out in colorectal cancer cases and our results further contributes to these limited studies." (PMID 33237662, 2021). "In colorectal cancer, eIF4A1 is overexpressed in 86% (44/51) of primary colorectal tumors compared to adjacent normal tissues according to immunohistochemical staining." (PMID 34869305, 2021). "It has been reported that miR-133a plays a pivotal role in colorectal cancer by inhibiting cell proliferation, invasion, and migration by targeting oncogenic eukaryotic translation initiation factor 4A1 (EIF4A1) in colorectal cancer." (PMID 31088567, 2019). "Thus, drugs, such as 15d-PGJ2 targeting the eukaryotic initiation factor 4A-I (eIF4A1) in the stress granules, can inhibit proliferation and induce apoptosis of leukemic and colorectal cancer cells." (PMID 35628304, 2022). "The mRNA levels of CPEB4, APC, TRIP13, EIF2S3, EIF4A1, IFNg, PIK3CA and CTNNB1 genes expressed in colorectal cancer tissue specimens, colorectal cancer blood samples, normal colon tissues and blood samples were analysed." (PMID 33237662, 2021). "The aim of the study is to assess expression levels of CPEB4, APC, TRIP13, EIF2S3, EIF4A1, IFNg, PIK3CA and CTNNB1 genes in tumors and peripheral bloods of colorectal cancer patients in stages I–IV." (PMID 33237662, 2021). "In addition to this evaluation, although there is not much study on EIF2S3 and EIF4A1 mRNA changes in cases with colorectal cancer, upregulation in peripheral blood draws attention in our study." (PMID 33237662, 2021).
lymphoma (6 papers, 2020 to 2025). A malignant (clonal) proliferation of B- lymphocytes or T- lymphocytes which involves the lymph nodes, bone marrow and/or extranodal sites. "A recent study showed that decreased eIF4A1 levels suppress lymphomagenesis in murine MYC-driven lymphoma, suggesting that eIF4A1 is a viable target for cancer therapy." (PMID 39779613, 2025). "Hence, eIF4A1 inhibition could be a new and effective treatment for aggressive and MYC+/BCL2+ lymphomas." (PMID 33562682, 2021).
cervical cancer (4 papers, 2021 to 2024). A primary or metastatic malignant neoplasm involving the cervix. "eIF4A1 overexpression has been detected in 83.9% of cervical cancer tissues and is significantly related to advanced tumor stage, lymph node metastasis, squamous cell histology, deep stromal invasion, and poor survival in patients with cervical cancer." (PMID 34869305, 2021).